APP (amyloid beta precursor protein)
Diseases named in the same sentence as APP in open-access papers (continued):
Sharing a sentence is not in itself a finding about the gene and the disease.
Alzheimer disease (continued). "Throughout the progression of Alzheimer’s disease, the synaptic transmission-expressed VGLUT2 protein demonstrates downregulation in the absence of both APP and amyloid precursor-like protein 2 (APLP2)." (PMID 38370359, 2024). "It is important to note that the GPCRs in the right cluster relate to APP and BACE1, which, while not ideal targets themselves, are well-known in their involvement with Alzheimer’s disease." (PMID 38276010, 2024). "As the main active component of ICA metabolite, ICII can suppress Aβ production via promoting the non-amyloidogenic APP cleavage process and markedly decrease the phosphodiesterase-5A (PDE5A) expression to treat Alzheimer’s disease." (PMID 37547333, 2023). "Since APP and APP/PS1 transgenic mice models do not show frank neuronal death, their importance in understanding the pathogenesis of Alzheimer’s disease is now questionable by taking into account their poor translational value." (PMID 37693644, 2023). "In our APP/PS1+Tau model, the tau expressed is wild-type human tau without endogenous mouse tau, making this relevant to early Alzheimer’s disease." (PMID 31825838, 2019). "The amyloid precursor protein (APP) interacts with the tropomyosin receptor kinase A (TrkA) in normal rat, mouse, and human brain tissue but not in Alzheimer’s disease (AD) brain tissue." (PMID 28197073, 2017). "The fact that the mild increase in total microglial numbers in both APP/PS1 and human Alzheimer’s disease is not justified by the reported high rates of proliferation indicates the necessity of compensatory microglial death." (PMID 26747862, 2016). "BACE1 competes with BACE2 over APP substrate, but their enzymatic activity generates different type of products in which the product of BACE1 but not BACE2 leads to Alzheimer's disease." (PMID 25254246, 2014). "Similarly, brain but not adipose data from Alzheimer's disease transgenic rodent studies using diet-induced obesity paradigms have indicated that obesity correlates with increased levels of brain Aβ although not necessarily an increase in full length APP as we observed." (PMID 22276186, 2012). "These alterations recapitulate many of the early cerebral vascular changes seen in AD patients, which are not seen in the 5x familial Alzheimer’s disease (FAD) transgenic mouse model, in which the overexpression of APP is targeted to neurons by the Thy1 promoter." (PMID 40141075, 2025). "In addition, BMP4 overexpression did not change the protein level of APP at 1 month and 3 months of age of transgenic mice, indicating that BMP4 overexpression-induced Alzheimer’s disease needs a progressive process." (PMID 33723239, 2021). "One possible explanation for this is that amyloid plaques in this Alzheimer’s disease mouse model are more abundant in the cortex than in the hippocampus, which could explain why MCP-1 levels were significantly increased in the brain cortex but not in the hippocampus of APP/PS1 mice." (PMID 28420415, 2017).
amyloid (981 papers, 2004 to 2026). "Both the TgCRND8/ChATChR2 AD mice and the TgF344 AD rats harbor human APP mutations, resulting in amyloid-driven AD pathologies." (PMID 39623428, 2024). "Intensities of ApoE-positive signals in the amyloid plaques and levels of ApoE and α1-antichymotrypsin in the soluble fraction were significantly elevated by the Mme deficiency in the 24-mo-old APP-Tg mice." (PMID 39348937, 2024). "The pathological hallmark of AD, amyloid-β plaques, originates from the imprecise cleavage of the amyloid precursor protein (APP) by β-secretase (BACE1) and γ-secretase generating amyloid-β peptide forms." (PMID 38902659, 2024). "For example, complete depletion of adaptive immunity through a knockout of the Rag2 gene showed either beneficial or detrimental effects in 5xFAD and APP/PS1 models of amyloidosis that were linked to amyloid plaque load and microglial activation." (PMID 38600001, 2024). "The APP S198P mutation in the N-terminal region of APP has been found to increase amyloidosis in cultured cells and transgenic mouse models." (PMID 37307834, 2024). "MAO-B reversibly increases astrocytic γ-aminobutyric acid (GABA) production in reactive astrocytes, which is associated with synaptic and memory impairments in APP/PS1 mice with amyloidosis." (PMID 38502413, 2024). "The lipid metabolism cluster contained APOE, which is genetically associated to AD, and APP, the precursor that produces the peptides found in amyloid plaques." (PMID 38104170, 2023). "The effects of Trem2 deficiency on amyloid pathology have been studied in APP transgenic mice with different results based on the mouse model used and the stage of amyloid pathology." (PMID 37274212, 2023). "Mutant variants of CST3 form deposits with APP peptides in senile plaques and arteriolar walls in the brain of AD patients, suggesting a role in amyloidosis." (PMID 36875133, 2023). "Supporting these in vitro findings, DISC1 overexpression in APPswe/PS1ΔE9 (APP/PS1) mice reduced amyloid plaque density, synaptic loss and cognitive defects, through the promotion of mitophagy." (PMID 35665766, 2023). "Deficiency of the WNT receptor LRP6 exhibited increased APP processing and exacerbated Aβ pathology in an amyloid mouse model." (PMID 37190113, 2023). "In Aβ pathology, altered amyloid precursor protein (APP) metabolism with the overproduction of Aβ peptides is the primary cause of amyloidosis, and APOEε4 and ABCA7 were identified to be most strongly associated with Aβ production." (PMID 38094504, 2023). "Tg2567 mice overexpress a mutated human APP gene with the Swedish mutation (APPswe), resulting in increased levels of amyloid-beta and amyloid plaques." (PMID 36939025, 2023). "This is supported by the weak association between amyloid plaques and memory impairments in mice expressing human APP (hAPP) and conversely by the observation of memory impairments in AD mouse models that lack amyloid depositions." (PMID 38203429, 2023). "In accordance with these in vitro data, CD33-deficient APP/PS1 mice show reduced brain levels of insoluble Aβ1-42 as well as amyloid plaque burden." (PMID 36359817, 2022). "Here, we describe two strategies for harnessing the wide range of Cre and CreER driver lines to control expression of disease-associated amyloid precursor protein (APP) in modeling Alzheimer's amyloid pathology." (PMID 35394029, 2022). "While most AD mice models bearing APPswe mutations begin plaque deposition around 2-month-old, APP/lon mice show first signs of amyloid deposition at age of 10 months old." (PMID 35235058, 2022). "In fact, no increase in mINS in the FC was observed in the transgenic mouse line PS2APP [PS2N141I × APP(swe)], which develops an age-related cognitive decline associated with severe amyloidosis." (PMID 35686025, 2022).
amyloid (continued). "Immunoprecipitation for specific splice variants of AD-related amyloidosis revealed that full-length APP splice variants APP751 and APP695 were greater in the prefrontal cortex in the WD-AB group (P ≤ 0.05)." (PMID 34027891, 2021). "Collectively, the CPA data strongly suggest that APP transgene activates microglia/macrophages, and myeloid Arg1 deficiency during amyloidosis promotes oligodendrocytes, by which CNS cell types presumably drive the regulation of neurodegeneration." (PMID 34046031, 2021). "Pharmacologic miR‐425 replacement targeting the normalization of APAM gene networks is possible, as we find that miR‐425 supplementation reverses the changes of target genes associated with disease and attenuates amyloid plaque formation in APP/PS1 mice." (PMID 34510683, 2021). "When brain iron metabolism is disordered, iron will be enriched in different regions of the brain, and the enriched iron will cause oxidative stress, mediate APP undergoing the amyloidosis pathway, and finally lead to the development of AD." (PMID 34830326, 2021). "In particular, various studies indicate that progressive amyloidosis and APP overexpression, neurons loss in the hippocampal CA3 area, and related cognitive impairment are not transitory, but a permanent sequela of TBI." (PMID 34065584, 2021). "The inclusion of human mutations associated with amyloid pathology, APPswe and PS1de9 (APP/PS1), highlighted these strain-specific differences in neuroinflammatory responsiveness." (PMID 33567283, 2021). "Our results showed that lactic acid targets APP and AD-associated pathways and are associated with amyloidosis, amyloid beta deposits, tau protein deposits, neurodegeneration, and other core AD phenotypes." (PMID 34670619, 2021). "In the present analysis genes that are known to be mutated in human inherited amyloidosis forms, such as APP, and TTR had variants matching the reference sequence." (PMID 33863921, 2021). "First, our results showed the APP transgene activated Aβ plaque induced genes (PIGs) as the top changed signature and myeloid Arg1 deficiency during amyloidosis up-regulated it further." (PMID 34046031, 2021). "Second, we demonstrated that APP transgene mostly activated microglia/macrophages and myeloid Arg1 deficiency during amyloidosis promoted oligodendrocytes by analyzing cell-type-specific gene expression." (PMID 34046031, 2021). "Our results showed that the neuronal FT deletion mitigates memory impairment and amyloid neuropathology in APP/PS1 mice through suppressing amyloid generation and reversing the pathogenic hyperactivation of mTORC1 signaling." (PMID 34315531, 2021). "5xFAD is an amyloid pathology model that expresses human APP and PSEN1 transgenes with a total of five AD-linked mutations." (PMID 33003412, 2020). "Several APP mutations have been identified that are associated with familial early‐onset amyloidosis." (PMID 33155752, 2020). "These are the cases of several rare familial genetic conditions termed hereditary hemorrhages with amyloidosis, caused by a mutation on the APP gene located on chromosome 21." (PMID 31847365, 2019). "In 4-month-old mice, the number of BrdU+ cells correlated positively with the extent of cell-associated amyloid in the DG of APP/PS1 mice (BrdU vs. cell-associated amyloid: r = 0.593, p = 0.015)." (PMID 29563870, 2018). "Similar amyloidosis is found already at a young age in the brains of patients with DS, caused by the inheritance of an extra copy of chromosome 21 that harbors the APP gene." (PMID 28103298, 2017). "To focus on the development of amyloid pathology, we used young AD transgenic Tg19959 mice harbouring two familial AD mutations in the amyloid precursor protein (APP), which show initial amyloid plaques at or just before 3 months of age12." (PMID 28287086, 2017). "APP/PSEN1 TG mice exhibit early amyloidosis as early as 4–6 months of age, reported to be associated with neuroinflammation and accumulation of cytokines." (PMID 29186131, 2017).
amyloid (continued). "Mice containing mutations in the amyloid precursor protein (APP) gene are the oldest and most widely studied models of AD, and are used to investigate the role of APP, amyloid-beta and amyloidosis in neurodegeneration." (PMID 25700953, 2015). "Administration of AFFITOPE-vaccines to APP-transgenic mice was found to reduce their cerebral amyloid burden, the associated neuropathological alterations and to improve their cognitive functions." (PMID 25611858, 2015). "As the amyloid burden is associated with both Aβ production and clearance, we further investigated the metabolism of APP after parabiosis." (PMID 26363791, 2015). "It is extensively reported to be regulated in other neurodegenerative disease models and in particular it is well known to interact with APP to promote amyloid plaque formation —a hallmark of AD." (PMID 24898206, 2014). "Most of these models have been generated by transgenic overexpression of the gene encoding for the human APP, which leads to progressive accumulation of Aβ and amyloidosis in the brain." (PMID 24659966, 2014). "Studies involving transgenic mice harboring mutations in AD-associated genes including amyloid precursor protein (APP), presenilin-1 and tau, have provided insights into possible reciprocal interactions between cholinergic markers and amyloidosis/tauopathy." (PMID 25674054, 2014). "This contrasts with our inability to discern improvements in spatial or associative memory deficits or reductions in amyloid deposits in APP+PS1 mice offered the KD." (PMID 24069439, 2013). "We also propose that axonal transport defects and synapse dysfunction caused by APP upregulation in our Drosophila model system occur prior to accumulation of amyloid plaques and severe neurodegeneration, similar to that described for a mouse model." (PMID 24086147, 2013). "The next step was to determine if the ApoBSecNEP protein traffics into the brain of APP tg mice and if it reduces the pathology and deficits associated with amyloid production." (PMID 21304989, 2011). "Tg2576 mice harbor the human APP transgene with the Swedish mutation and develop AD-like amyloidosis and memory deficits." (PMID 20862226, 2010). "Transgene regulated over-expression of the M1-stimulating cytokine, interleukin-1 in APP mice caused reductions in amyloid pathology." (PMID 20846376, 2010). "The APOE4 ε4 genotype is associated with increased brain amyloid load in AD patients and normal individuals, as well as in APP Tg mice." (PMID 21034469, 2010). "Earlier studies with vaccines against the Aβ peptide demonstrated protection from the learning and memory deficits associated with amyloid accumulation in APP-transgenic mice." (PMID 15588287, 2004). "As synaptic dysfunction is one of the key mechanisms associated with cognitive deficits in dementia, we investigated the effect of rTMS on cortical synapses using an APP/PS1 amyloidosis mouse model of AD crossed with fluorescent reporters linked to the Thy-1 promoter." (PMID 40438149, 2025). "Murine models, typically genetically engineered to express APP mutations, develop amyloid plaques." (PMID 40867608, 2025). "According to the predictions, the extent of advanced amyloidosis suggests that our case may represent a gain-of-function (GoF) mutation, affecting the amyloidogenic pathway of APP." (PMID 41551043, 2025). "Second, while the APP/PS1 transgenic model successfully recapitulates key features of amyloid pathology, including plaque formation and associated neuroinflammation, it lacks other critical characteristics of human AD, most notably tau pathology and neurofibrillary tangles." (PMID 41226060, 2025). "However, αsyn ablation in APP/αsyn-KO mice caused increased amyloid burden and rescued APP-driven cognitive deficits." (PMID 40269912, 2025). "In addition, Srf-deficient astrocytes in the APP/PS1 model of AD resulted in a greater reduction of amyloid plaque burden in the cortex and hippocampus." (PMID 38289036, 2024).
amyloid (continued). "Thus, amyloid plaque depositions suggest that the age-associated amyloidosis in APP/PS1 mice increase throughout disease progression." (PMID 38023614, 2023). "Crossing eNOS knockout (eNOS−/−) mice with a mouse model of amyloid pathology (APP/PS1 mice) was associated with increased phosphorylated tau (p-tau), which was attributed to an increase in Cdk5 activation by p25, while other kinases, such as GSK-3β, were unchanged." (PMID 37238700, 2023). "Amyloid plaques formed by the accumulation of Aβ are a pathological hallmark of AD and lead to neurite damage, which is causally related to neuroinflammation in APP/PS1 transgenic mice." (PMID 36185476, 2022). "In AD, for example, amyloid precursor protein (APP) is cleaved to release Aβ1–42 peptide which accumulates as amyloid foci in affected brain regions; familial-AD mutations in APP, such as APPSw, strongly predispose to the development of amyloid foci and AD dementia." (PMID 34347206, 2022). "Muscle can be a useful system for studying APP-induced toxicity, as APP-derived amyloid pathology in muscle similar to that seen in AD brain is associated with inclusion body myositis, a muscle disease, and APP.C99 transgenic mice have been used to model inclusion body myositis." (PMID 36170200, 2022). "Amyloid plaques and hyperphosphorylation of Tau are hallmarks of AD, and one potential mechanism underlying accumulation of aggregates involves dysregulation of APP processing that can lead to overproduction of Aβ." (PMID 36497141, 2022). "Given the role of eNOS-derived NO in modulating APP processing and in maintaining cerebrovascular function, we postulated that partial eNOS deficiency might exacerbate amyloid plaque load and other AD-like pathology in the hippocampus of APP/PS1 mice." (PMID 35806318, 2022). "Increased APP is associated with increased Aβ production and amyloid plaque formation." (PMID 35360155, 2022). "Our results demonstrate that abnormal upregulation of FT occurs in the early stage of human AD, and suppressing neuronal FT alone confers neuroprotective benefits against cognitive deficits and amyloid pathology through reversing pathogenic hyperactivation of mTORC1 signaling in APP/PS1 mice." (PMID 34315531, 2021). "Notably, we recently showed that δCOP regulates Aβ production via regulating APP retrograde trafficking, and mutation of δCOP significantly decreases amyloid plaque formation while enhancing cognitive function in an AD mouse model in vivo." (PMID 34156424, 2021). "However, we recently found peripheral IR in an early-asymptomatic phase of the disease in young AD-relevant amyloidosis mice overexpressing the human APP with the Swedish double mutation [B6.Cg-Tg(Thy1-APP)3Somm/J, referred to as APP23]." (PMID 33855048, 2021). "Our analysis suggests that glutamic acid targets APP and may be associated with amyloidosis, amyloid beta deposits, tau protein deposits, and neurodegeneration." (PMID 34670619, 2021). "The 5xFAD mouse model used in the current study is characterized by increased APP expression early in life, modeling familial AD, with pronounced, early amyloid pathology, neuronal loss, and changes in spine density in the somatosensory and prefrontal cortex by ∼6 months of age." (PMID 33453282, 2021). "For instance, the APP23 mice, overexpressing the mutant human-type APP protein with the Swedish mutation (K670M/N671L), is a widely used animal model of AD since it genetically develops amyloidosis and presents cognitive and behavioral symptoms similar to those found in patients." (PMID 34199476, 2021). "Taken together, the present study provides preclinical evidence that inhibition of JNK3 phosphorylation by PBM treatment can effectively rescue AMPA receptor endocytosis and dramatically reduce amyloid load, neuroinflammation, and synaptic loss in APP/PS1 transgenic mice." (PMID 33336891, 2021).